CFAP263 (cilia and flagella associated protein 263)
Description:
Component of centriolar satellites contributing to primary cilium formation. In complex with CFAP263, acts as a regulator of ciliary beating that connects radial spoke 3 (RS3) to the inner dynein arm (IDA) and the nexin-dynein regulatory complex (N-DRC). The complex is positioned parallel to N-DRC and forms a connection between the arch at the base of RS3, the IDA tail and N-DRC (By similarity).
Synonyms: CCDC113; HSPC065; DKFZp434N1418
Tractability: Small molecule: a structure with a bound ligand is known. PROTAC: ubiquitination databases record sites on it.
Gene: Protein-coding gene on chromosome 16 (58,231,157 to 58,283,836, forward strand). Ensembl gene ENSG00000103021.
Subcellular location: Cytoplasm, cytoskeleton, microtubule organizing center, centrosome, centriolar satellite; Cell projection, cilium
Gene Ontology:
Molecular function: protein binding
Biological process: cilium assembly
Cellular component: centriolar satellite; ciliary basal body; protein-containing complex; axoneme; cilium
Genetic constraint (gnomAD): Loss-of-function variants: 38 observed, 30.91 expected, observed/expected ratio (o/e) 1.23, 90% interval 0.95 to 1.61. The upper end of that interval is the gene's LOEUF score, 1.61, which puts it in group 6 of 6, group 1 being the genes least tolerant of losing a copy. Missense variants: 334 observed, 355.65 expected, observed/expected ratio (o/e) 0.94, 90% interval 0.86 to 1.03. Synonymous variants: 125 observed, 129.92 expected, observed/expected ratio (o/e) 0.96, 90% interval 0.83 to 1.12.
Homologues: Orthologues: chimpanzee CFAP263 (98% identical), macaque CFAP263 (93% identical), pig CFAP263 (81% identical), dog CFAP263 (80% identical), rat Ccdc113 (79% identical), guinea pig CFAP263 (79% identical), mouse Ccdc113 (78% identical), rabbit CFAP263 (77% identical), tropical clawed frog cfap263 (49% identical), zebrafish cfap263 (35% identical).
Diseases named in the same sentence as CFAP263 in open-access papers:
CFAP263 is named in the same sentence as 15 diseases in open-access papers, as found by Europe PMC text mining. Sharing a sentence is not in itself a finding about the gene and the disease.
CFAP263 shares sentences with these, for which no sentence is quoted: asthma (2 papers); autoimmune disorders (1); cancer (1); ciliopathies (1); colorectal cancer (1); cone-rod dystrophy (1); Hydrocephalus (1); Infertility (1); lung carcinoma (1); male infertility (1); Optic neuropathy (1); primary ciliary dyskinesia (1); retinitis pigmentosa (1); situs inversus (1); tumor (1).